BRAF (B-Raf proto-oncogene, serine/threonine kinase)
Diseases named in the same sentence as BRAF in open-access papers (continued):
Sharing a sentence is not in itself a finding about the gene and the disease.
colon carcinoma (continued). "We have identified an alternative pathway of tumorigenesis in sporadic colon cancer, involving microsatellite instability due to mismatched repair methylation, which may be driven by mutations in the BRAF gene (V600E)." (PMID 18718023, 2008). "Participation in the study provided an opportunity for BRAF testing, which may have led investigators to preferentially enroll patients with characteristics indicative of BRAF V600E mutations, such as right-sided colon cancer or peritoneal dissemination." (PMID 39941768, 2025). "Therefore, we chose two genetically identical colon cancer cell lines with the BRAF mutation." (PMID 38256402, 2024). "Therefore, tumors of the right colon have BRAF mutations more frequently; they present in a more advanced stage of the disease and are associated with a higher rate of post-surgical complications and a poorer prognosis than left colon tumors." (PMID 37893479, 2023). "Taken together with the previous studies, the present findings suggest that the ability of reagents that interfere with PCs, particularly Furin, could potentially have therapeutic effects by regulating calcium regulators in colon cancer with KRAS or BRAF mutation." (PMID 35267511, 2022). "Immunotherapies may become fundamental treatments for BRAF mutated colon cancer in the future." (PMID 34381786, 2021). "Thus, multi-drug nature of the proposed novel therapeutic strategy could contribute to increased treatment response in BRAF mutated colon cancer cells." (PMID 34639107, 2021). "Our data revealed that a co-treatment with vemurafenib and ABC294640 significantly reduced cellular levels of S1P in comparison with either drug alone, which again confirms that the aberrant regulation of S1P metabolism might be a hallmark of drug resistance in BRAF mutant colon cancer cells." (PMID 34639107, 2021). "Altogether, the obtained data point to the relevance of S1P metabolism in the development of resistance to vemurafenib and indicate that targeting S1P production by the SphK2 inhibitor ABC294640 could increase the sensitivity of BRAF mutated resistant colon cancer cells to vemurafenib." (PMID 34639107, 2021). "Microsatellite stable colon cancer models with BRAF or KRAS mutations in Subgroups II and IV have shown responses to the combination of EGFR (cetuximab), MEK (trametinib), and/or RAF (regorafenib) inhibition, providing a strong hypothesis for further evaluation." (PMID 34885128, 2021). "Since KRAS and BRAF gene mutations are frequently present in colon cancers and have adverse prognostic significance, we examined whether mutations in these genes were more prevalent in tumors with high STAT1 expression, which could have contributed to poor prognosis." (PMID 32275681, 2020). "BRAF genotypes are often assayed in colon cancer, either by immunohistochemistry or other molecular assays as activating BRAF mutations are also a relative contraindication to EGFR targeted therapy, and BRAF status may play an additional role in Lynch syndrome screening." (PMID 29698444, 2018). "Our observations suggests that within the left-sided group, there is a decrease of BRAF mutation rate from left colon to rectum and that the different BRAF mutation rates might contribute to the different behavior of left- and right-sided colon cancers and rectal cancers." (PMID 29156800, 2017). "Information about the tumor genotype, and in particular about mutations in PI3K/AKT, KRAS and BRAF are currently used to predict the success of systemic chemotherapy of different types of tumors and are used to stratify patients for treatment options for example in colon cancer." (PMID 26799289, 2016). "Indeed, although recently the combination of standard chemotherapy with bevacizumab has been proposed as the best therapeutic option for BRAF-mutated advanced CRCs, the prognosis of these patients is still dismal compared to other molecular subtypes of colon cancers." (PMID 26084290, 2015).
colon carcinoma (continued). "Furthermore, the BRAF mutation could be detected in paraffin-embedded tissues of colon cancer that had been previously diagnosed by Sanger dideoxy sequencing." (PMID 23274581, 2013). "Some case-control and cohort studies have reported a poor prognosis associated with CIMP in combination with microsatellite stable tumors, although this may reflect the co-occurrence of BRAF V600E mutations, which have been associated with significantly poorer survival in colon cancer." (PMID 21559209, 2011). "Although BRAF V600E‐positive GBMs account for only 3% of whole cases, the BRAF‐FOSL1 axis appears to be potentially relevant, given that BRAF is the upstream signaling molecule of FOSL1 in colon cancer and that both molecules share the MAPK signaling pathway." (PMID 41556041, 2026). "We have found that correction of the V600E mutation in BRAF results in demethylation of CIMP genes and of PRC2 target genes in colon cancer organoids." (PMID 40678543, 2025). "BSC only rates were the lowest among RAS&BRAFwt rectal cancers (18%) and the highest among BRAF-V600Emt right colon cancers (40%)." (PMID 40437037, 2025). "In colon cancer, 36.8% of patient samples were RAS/BRAF‐wt and 63.2% had a known or likely pathogenic RAS/BRAF alteration, respectively." (PMID 39865537, 2025). "Meanwhile, the randomized phase 2/3 study A022004 aims to treat patients with encorafenib and cetuximab versus usual care in the adjuvant setting for patients with stage 2B and stage 3 colon cancer (CC) with BRAF V600E." (PMID 41294686, 2025). "Supporting previous findings that BRAF-V600E colon tumors are resistant to treatment with vemurafenib,19Smad4f/f; BrafV600E/+ organoids were not sensitive to vemurafenib alone, or to treatment with erlotinib." (PMID 39626159, 2024). "These associations match with observations that colon cancers with low CDX2 expression predominantly occur in the proximal side of the colon (p-val < 0.001) and/or in the context of BRAF mutation (p-val < 0.001) 19,46." (PMID 38360902, 2024). "Consistent with the notion that mutant BRAF-driven right-sided colonic tumors are fetal progenitor phenotypes, GSEA results confirmed enrichment of the fetal-type transcriptomic signatures in cecal mucosa in BC mice." (PMID 38921956, 2024). "A particular correlation that was observed was between cigarette smoking and the risk of colon cancer, but only in a subset of tumors that were CIMP high and BRAF wild type, or CIMP high and BRAF mutation, along with KRAS wild type." (PMID 38464391, 2024). "To elucidate the functional link between WDR5 expression and response to chemotherapy, we next analyzed datasets of a recently published human colon cancer-patient clinical trial for combined PD-1, BRAF, and MEK inhibition." (PMID 39201460, 2024). "The data demonstrate rapid clonal dynamics in response to effective therapies in BRAF-V600E-mutant colon cancer that can be monitored by serial cfDNA analysis." (PMID 39626159, 2024). "The mutually exclusive BRAF and KRAS mutations provide alternate means of activating the MEK-ERK signaling pathway and function as critical cancer driver mutations in colon cancers." (PMID 38360902, 2024). "In a multivariate analysis, we identified male sex, age ≥50, colon tumors, early-stage tumors, NRAS mutant tumors, and BRAF wild-type tumors as risk factors for CRC patients with high-risk polyps." (PMID 38978992, 2024). "The rationale behind this study is that patients with mismatch-repair-proficient, BRAF V600E-mutant, high-risk, stage II or III colon cancer face a significant risk of recurrence, despite receiving standard adjuvant therapy." (PMID 38790167, 2024). "It has been reported that NRG-1β activates ErbB-3 to promote Vemurafenib resistance in BRAF(V600E) colon cancer stem cells (CSCs)." (PMID 39052013, 2024).
colon carcinoma (continued). "Consistent with the notion that mutant BRAF-driven right-sided colonic tumors are fetal progenitor phenotypes, GSEA results confirmed enrichment of the fetal-type transcriptomic signatures 41 in cecal mucosa in BC mice." (PMID 36778401, 2024). "While BRAF mutations and MSI were more common in proximal colon cancer patients, this was only less than 5% in the distal colon cancer patient population." (PMID 39113889, 2024). "Previously, we demonstrated that ETBF-induced BRAF mutant colon tumors are characterized by a mucinous phenotype." (PMID 38893159, 2024). "The current findings suggest that male gender, age ≥50, colon tumors, early-stage tumors, NRAS mutant tumors, and BRAF wild-type tumors are risk factors for CRC with high-risk polyps." (PMID 38978992, 2024). "The results indicated that PTEN mutations are associated with proximal colon tumors, mucus histology, MSI-H, CIMP-high (CIMP-H), and BRAF mutation." (PMID 39113889, 2024). "Combining ERK inhibitors with BRAF inhibitors in several tumor types and BRAFV600E mutated colon cancer exhibits a similar synergism, with SHP2 inhibition as promising additional partner." (PMID 38504984, 2024). "Altogether the hypermethylated CEACAM5 group showed these clinical features resemble the CMS1 classification of CRC with a BRAF mutation, TGFB2 mutation, MSI‐H, and proximally located colon tumor." (PMID 37942534, 2024). "The remaining patients were patients with right or left colon tumors and we compared the OS, molecular mutations (KRAS, NRAS, BRAF, MSI status), and clinicopathological features of our patients with transverse colon tumors with these patients." (PMID 39629291, 2024). "In the univariate analysis, male sex, age ≥50, colon tumors, early-stage tumors, NRAS mutant tumors, and BRAF wild-type tumors were significantly associated with an increased risk of high-risk polyps." (PMID 38978992, 2024). "Detection of BRAF in colon carcinoma has the potential as a prognostic marker and also as treatment target for new BRAF inhibitors, such as vemurafenib." (PMID 36673047, 2023). "Another study used nanoparticles to treat colon carcinoma, combining a BRAF inhibitor with miR‐200c, which can downregulate PD‐L1 expression and participate in the enhancement of the anti‐tumour immune response." (PMID 36718025, 2023). "Oncogenic mutations activating the WNT signaling pathway were a universal feature of serrated tumors in the model Smad4KO BRAFV600E/+, indicating that the combination of BRAF, SMAD4, and WNT mutations is critical for the progression of serrated colon cancers." (PMID 38136364, 2023). "Specifically, BRAF protein expression was higher in rectal tumors compared to colon tumors (p =0.077)." (PMID 38023196, 2023). "Studies found that NRG1-induced HER3 activation induced resistance to BRAF V600E inhibitor vemurafenib in colon cancer." (PMID 37947595, 2023). "In accordance with these findings, anti-HER3 antibodies restore sensitivity to vemurafenib in BRAF-V600E mutant colon cancer." (PMID 37947595, 2023). "In this study containing 43 BRAF mutant colon cancer, the expression of CD8+ T cells was found to be significantly higher in BRAF mutant colon cancer patients than in wild-type ones (P < 0.001)." (PMID 37302081, 2023). "It has been shown that right-sided colon tumors commonly present with poor prognostic factors such as RAS and BRAF mutations other than microsatellite instability (MSI)." (PMID 36765570, 2023).
colon carcinoma (continued). "And a higher DRP1 level was also presented in colon cancer cells with BRAF V600E than in BRAF WT cells." (PMID 36647167, 2023). "Polygonum barbatum extract (PBE) and quercetin standard HPLC fingerprints were determined using analytical RP-HPLC and evaluations were completed using the human colon cancer cell line HCT-116 (KRASG13D mutation) and HT-29 (BRAF mutation) cells." (PMID 37884620, 2023). "As demonstrated in this study, this complex efficiently suppressed three human colon cancer cells: double wild type; BRAF mutant; and KRAS mutant." (PMID 37099199, 2023). "And BRAF V600E mutant CRCs were more likely to have right‐side colon tumor, lymph node and peritoneal metastases." (PMID 36912150, 2023). "This article reports a rare and challenging case of advanced RAS and BRAF wild-type colon cancer combined with cirrhotic decompensation." (PMID 37741975, 2023). "This is important, considering that APC mutations have been shown to cooperate with BRAF and KRAS mutations for the development of colon cancer, which are also genetic alterations present in HT-29 and SW480 cells, respectively." (PMID 37259421, 2023). "Previous studies found that PTPN11 shRNA or CRISPR/cas9-mediated deletion prevented adaptive resistance to vemurafenib in BRAF mutant colon cancer." (PMID 37325052, 2023). "A beneficial synergism of CTLA-4 blockade with BRAF inhibition was shown in BRAF-wildtype colon carcinoma and fibrosarcoma mouse models." (PMID 36168618, 2022). "In this current study, because of this reason and their different genetical background (HT-29 cell line is BRAF-mutated colorectal adenocarcinoma; on the other hand, the HCT-116 cell line is KRAS-mutated colon carcinoma), we have selected these lines." (PMID 36547904, 2022). "CDX2 status, tumour location, tumour size, TILs, KRAS and BRAF status were ranked of lowest importance in determining prognosis in colon cancer." (PMID 35323316, 2022). "The evidence for BRAF V600E as a biomarker in guiding recommendations for adjuvant chemotherapy in stage II colon cancer is scant." (PMID 35323316, 2022). "The possible explanation is that the different intrinsic biological behaviors of the right and left colon cancer and the higher rate of BRAF mutant cases in right colon cancer are related to a more aggressive clinical behavior." (PMID 35251979, 2022). "Immunohistochemistry analysis of 351 colon cancer tissue specimens for mutant BRAF revealed positive staining in 60 samples, while 291 samples were not stained." (PMID 35454158, 2022). "In colon tumors, GZMB has been shown to be highly expressed in the proximal colon and is characterized by MSI-high and BRAF mutations, with higher levels of GZMB being associated with longer OS and CSS." (PMID 35846123, 2022). "Therefore, the analysis of EGFR and RAS/BRAF mutations in plasma using the IdyllaTM platform is feasible and reliable in clinical practice and allows the selection of the best treatment for our patients, especially those with metastatic lung adenocarcinomas and colon cancer." (PMID 36497340, 2022). "This study revealed that BRAF and MMR gene mutations were lower in the metastatic colon cancer tissues than in the primary tumor tissues." (PMID 35592200, 2022). "Another study indicated that right-sided colon cancers were associated with a high CpG island methylator phenotype (CIMP) and BRAF mutations, translating into inferior OS and a worse response to anti-EGFR treatment." (PMID 36230751, 2022).
colon carcinoma (continued). "Combined inhibition of BRAF and EGFR effectively improves the response of BRAF(V600E) colon cancers to BRAF inhibitors." (PMID 36483040, 2022). "Colon tumors that lack CDX2 expression are more prone to have aggressive characteristics such as advanced stage, poor differentiation, vascularization, BRAF gene mutation, and the CpG island methylator profile." (PMID 35721501, 2022). "In stage II and III colon cancer, studies have shown worse prognosis in BRAF V600E-mt patients, with increased mortality and reduced PFS." (PMID 35323316, 2022). "The combined inhibition of Hsp90 and CDC37 was efficient in abrogating the phosphorylation of Akt in mutant BRAF colon cancer cells." (PMID 36012578, 2022). "Another study demonstrated that right-sided colon cancers had higher rates of MSI, more frequent aberrant activation of the EGFR/MAPK pathway including higher BRAF mutation rates and an increased mutational burden compared to left-sided CRCs." (PMID 36230751, 2022). "As expected, the treatment of RKO cells with a dual SphK1/SphK2 inhibitor significantly increased cytotoxic effects of oxaliplatin, which suggests that SphK1 and SphK2 regulate chemosensitivity of BRAF mutant colon cancer cells." (PMID 34639107, 2021). "We also used NMF method to identify the sub‐consensus of colon cancer cell lines and found a sub‐consensus of colon cancer cells was sensitive to BRAF inhibitors and PI3K‐mTOR inhibitors." (PMID 34734491, 2021). "For example, the administration of sphingosine kinase inhibitor SKI increased oxaliplatin cytotoxicity and apoptosis induction in the BRAF mutant RKO colon cancer cell line." (PMID 34639107, 2021). "Collectively, our study suggests the possibility of using the combination of ABC294640 and vemurafenib as a novel therapeutic approach to combat vemurafenib resistance in BRAF mutant colon cancer." (PMID 34639107, 2021). "The present study seeks to address the role of bioactive sphingolipid species and the enzymes regulating their metabolism and signalling in the development of resistance to BRAF inhibition by vemurafenib in BRAFV600E mutant colon cancer cells." (PMID 34639107, 2021). "Importantly, the growth factor-dependent induction of TCTP protein expression levels in HT-29 cells could be dramatically reduced by pharmacological inhibition of AKT, which indicates that TCTP synthesis is regulated by the AKT pathway in BRAF mutated HT-29 colon cancer cells." (PMID 34639107, 2021). "Here, we have shown that an increased basal expression of NPM1 in BRAF mutant colon cancer cell lines coincides with an increased expression level of phospho-c-Myc (Ser62)." (PMID 34201061, 2021). "In BRAF-mutant colon cancer, cell resistance to vemurafenib (a BRAF inhibitor) is a result of the feedback activation for the MAPK signaling pathway by SEs, and an additional combination of related inhibitors can reverse this phenomenon." (PMID 34011395, 2021). "Accordingly, C16:0 and C22:0/24:0 ceramides should be further studied as potential resistance biomarkers, and their potential benefits in monitoring therapeutic efficacy of vemurafenib in BRAF mutant colon cancer should be further explored." (PMID 34639107, 2021). "BRAF mutation, SMAD4 loss, and KRAS mutation are all associated with inferior survival among patients with colon cancer." (PMID 33874958, 2021). "Despite activating the same pathway, BRAF mutant tumors have distinct expression signatures from KRAS mutant tumors in colon cancer." (PMID 34214079, 2021).